RRM2 (ribonucleotide reductase regulatory subunit M2)
Diseases named in the same sentence as RRM2 in open-access papers (continued):
Sharing a sentence is not in itself a finding about the gene and the disease.
tumor (continued). "To explore the clinical implications of RR subunits, we compared the differences of RRM1, RRM2, and RRM2B among clinicopathologic features, including age, race, gender, T stage, grade, stage, tumor status, and alpha-fetoprotein (AFP) level." (PMID 36713030, 2023). "In this study, we also found that RRM2 was upregulated in HCC with a higher clinicopathological grade, such as T stage, pathologic stage, tumor status, histologic grade, and AFP level." (PMID 37056349, 2023). "Seven pairs of tumor and adjacent non-tumorous tissues were selected to verify the expressions of the ZWINT, RRM2, NDC80, KIF4A, CEP55, CENPU, and CENPF genes." (PMID 35028418, 2022). "Then, we explored the connection between RRM2 expression and TIME, particularly immune checkpoints and tumor-infiltrating immune cells (TIICs)." (PMID 36518297, 2022). "For example, E2F1 was reported to promote tumor growth, invasion and metastasis of CRC cells by activating the ribonucleotide reductase small subunit M2 (RRM2) transcription." (PMID 35069909, 2022). "The results revealed that the mean methylation levels of G6PD, HELLS, RRM2, and STMN1 were significantly lower in HCC tissues than in peri-tumor tissues." (PMID 36304446, 2022). "The qPCR results revealed that the mRNA levels of RRM2, MIF, PANX1, and EGLN1 were significantly higher in tumor samples than in paired normal samples." (PMID 35311093, 2022). "Given that cyclin F, RRM2, and SPDL1 are considered GIN-related proteins, we also analyzed their expression in relationship to tumor aneuploidy score and fraction genome altered (TCGA cohort) or MSH6 protein level (our cohort)." (PMID 33670609, 2021). "The overexpression of this piRNA inhibited Ribonucleotide reductase subunit M2 (RRM2) and Cytochrome P450 1A2 (CYP1A2), two crucial factors for tumor growth and drug resistance." (PMID 34799689, 2021). "Noteworthy, co-administration of RRM2-siRNA and doxorubicin (DOX) can lead to synergistic effect and a four-fold increase in anti-tumor activity." (PMID 34943856, 2021). "The result of q-rtPCR showed that the mRNA expression levels of PTGS2, RRM2, AURKA, CAV1, MAP3K5, STEAPS are higher in tumor samples and lower in normal tissue samples and the others had the reverse tendency." (PMID 33819918, 2021). "The upregulated ACSL3, DDIT4, RRM2, and SLC2A1 with HR > 1 were considered as oncogenes, whereas the downregulated HERPUD1 and PEBP1 with HR < 1 were regarded as tumor suppressors." (PMID 34499810, 2021). "RRM2 expression induced by BRCA1, traditionally regarded as tumor suppressor, promotes tumorigenicity in GBM cells." (PMID 34568059, 2021). "Others have proposed that overexpression of the RRM2, GTSE1 and EXO1 genes in HNSCC have active roles in tumor progression and inhibition of the apoptosis pathway." (PMID 34231338, 2021). "We found cyclin F, RRM2, and SPDL1 to be overexpressed at both protein and mRNA levels in tumor tissues compared to respective controls." (PMID 33670609, 2021). "The results showed that the expression of RRM2 and KIF23 was significantly up-regulated in HCC tumor tissues compared with adjacent tissues (P < 0.001)." (PMID 34324544, 2021). "Serum RRM2 was also positively correlated with serum carcinoembryonic antigen (CEA) (R = 0.45, P < 0.0001), a tumor biomarker for the digestive tract." (PMID 33372599, 2020). "It was also reported that RRM2 promotes HCC cell proliferation, inhibits apoptosis in vitro, and promotes tumor growth in vivo." (PMID 32213663, 2020). "The expression of four proteins (MCM3, RRM2, NT5DC2, and RNASEH2A) was significantly upregulated in HCC tissues compared to that in non-tumor tissues." (PMID 32213663, 2020). "Lastly, the wet-lab qRT-PCR experiments compared the mRNA expressions of PPAT, ATIC, IMPDH1, DCK, and RRM2 in between 10 pairs of human primary HCC tissues and neighboring non-tumor liver tissues." (PMID 33520699, 2020).
tumor (continued). "We examined RRM2 protein expression in UALCAN database, discovering it was highly expressed in tumor tissues." (PMID 33123291, 2020). "Our IHC examination of NSCLC tumor tissue and immunofluorescent images of three cell lines in the HPA have demonstrated that both RRM1 and RRM2 are mainly expressed in the cytoplasm, whereas RRM2B is expressed both in the cytoplasm and the nucleus." (PMID 31637211, 2019). "Recently, it has been demonstrated that DHS inhibits DNA replication via its ability to interact with ribonucleotide reductase regulatory subunit M2 (RRM2) and decreases tumor growth of a wide spectrum of cancer cell lines." (PMID 30893846, 2019). "The results showed that RRM1 and RRM2 protein mainly localized in the cytosol while RRM2B protein was found in both the cytosol and nucleoplasm of LUSC and LUAD tumor cells." (PMID 31637211, 2019). "Since RRM2 regulates BCL-2 in various types of cancers and plays an active role in tumor progression, it can serve as a potential target for cancer therapy." (PMID 31064156, 2019). "RRM2-c2orf48 was found to be recurrent among NPC patients and enriched in tumor tissues at readily detectable levels, whereas it presents low levels of expression in noncancerous nasopharyngeal epithelial tissues." (PMID 28906488, 2017). "Our results indicate CREB1 as a critical transcription factor of RRM2 which promotes tumor aggressiveness, and imply a significant correlation between CREB1 and RRM2 in CRC specimens." (PMID 27801665, 2016). "Kaplan-Meier analysis showed a trend in shorter OS for patients with RRM2, TS, and ERCC1, BRCA1 overexpressed tumours." (PMID 26663950, 2015). "RNAi-mediated Knockdown of RRM1 and RRM2 +GEM, inhibiting tumor effect is the best among the four groups." (PMID 26658059, 2015). "For the first time, we found overexpression of RRM2 alone reduces TSP-1 expression; induced VEGF expression in tumor cells, resulted in a tumor xenograft with more angiogenic potential and accelerated growth in vivo." (PMID 19250552, 2009). "Increased RRM2 and RNR enzymatic activity were reported to present in highly metastatic tumor cells and tissues." (PMID 19250552, 2009). "Concurrently, tumor tissue and primary cultures displayed low transcript levels of proliferation-related genes, such as, TOP2A, ANKT, RAD51, UBE2C, CENPA, RRM2, and PLK." (PMID 15260889, 2004). "However, despite these valuable insights, the specific mechanisms by which RRM2 contributes to LUAD, particularly its interactions with the tumor immune microenvironment, remain underexplored." (PMID 41357570, 2025). "In this study, we performed a systematic differential expression analysis of RRM2 across 30 cancer types by integrating TCGA tumor data with both TCGA tumor-adjacent samples and non-diseased tissues from the GTEx database." (PMID 41333212, 2025). "This process is mediated through the MALAT1/miR‐143‐3p/RRM2 axis, wherein resveratrol downregulates the oncogenic lncRNA MALAT1, upregulates miR‐143‐3p, and inhibits the expression of RRM2, a known promoter of tumor progression." (PMID 40708783, 2025). "Our study identified RRM2 and GAPDH as hypomethylated and upregulated genes in LUAD, suggesting that their hypomethylation leads to increased expression, contributing to enhanced tumor aggressiveness, drug resistance, and poor patient prognosis." (PMID 40341308, 2025). "Importantly, multivariate Cox analysis confirmed RRM2 as an independent prognostic factor for LUAD (HR = 1.30, 95% CI: 1.14–1.53, p < 0.01), after adjusting for age, sex, race, tumor stage, and smoking status." (PMID 41357570, 2025).
tumor (continued). "Notably, RRM2 exhibited significant inverse correlations with let-7f-5p (R = -0.14525, P = 0.001), let-7b-3p (R = -0.23631, P = 7.29E-08), and let-7b-5p (R = -0.32575, P = 6.1E-14), suggesting that these miRNAs may function as tumor suppressors by negatively regulating RRM2 expression." (PMID 41357570, 2025). "The expression level of RRM2 in PTC tissues was much higher than that in paracancerous thyroid epithelial tissues, and the expression level of RRM2 was correlated with the size of the tumor (P<0.01)." (PMID 41333212, 2025). "According to our analyses, ADM exhibited positive correlation with metabolic reprogramming, particularly in purine (PPAT, GMPS, RRM1, and RRM2) and pyrimidine (CAD and UMPS) metabolic pathways, suggested that it played an important role in tumor cell metabolic adaptation." (PMID 40547013, 2025). "Finally, the biological role of RRM2 was validated in vitro (CCK-8 and colony-formation assays) and in vivo (subcutaneous tumor formation in nude mice)." (PMID 41333212, 2025). "Meanwhile, a TIMER database analysis revealed that, in various types of cancer, including HCC, the expression of RRM2 was specifically elevated in tumor tissue compared to adjacent noncancerous tissue." (PMID 39766842, 2024). "We found that membrane localization of RRM2 was only present in iCCA tumor cells but not in normal bile duct cells, hepatocytes or other cells of the tumor microenvironment." (PMID 39243109, 2024). "Using immunohistochemistry in tumor tissues from HCC patients who underwent curative hepatectomy, with viral and non-viral causes of HCC, one study showed the high RRM2 expression in 19 of 25 (76%) HCV-related HCC patients correlated with their poor prognosis." (PMID 36768940, 2023). "In addition, it was showed that the clinicopathological feature between BUB1B and RRM2 genes expression and HCC patients were significantly changed in age, fibrosis Ishak score, neoplasm histologic grade, pathologic T, race and tumor stage diagnoses." (PMID 36829489, 2023). "Taken together, our study suggest that RRM2 may function as an oncogene and play vital role in ATRT survival and progression, making it a promising therapeutic target for this aggressive tumor." (PMID 38124207, 2023). "The expression levels of RRM2 in LIHC tissues and paired adjacent non-tumor tissues were analyzed." (PMID 37056349, 2023). "Moreover, the expression of SNHG4, TK1, AURKA, RRM2 and EZH2 in the tumor tissues was found to be significantly elevated after SNHG4 overexpression." (PMID 37596700, 2023). "To verify whether RRM2 mediates the anti-tumor effect of PECT on GBM, we overexpressed RRM2 and exposed them to PECT, and founded that GBM cells viability were partially rescued with RRM2 expression upregulation." (PMID 35651787, 2022). "Next, we investigated the effect of RRM2 on TIME and evaluated whether RRM2 could be used as a biomarker of tumor cell response to immunotherapy and influence clinical outcomes via TIME parameters." (PMID 36518297, 2022). "RRM2 has been reported to be an independent predictor of early recurrence of HCC, indicating that RRM2 may facilitate tumor cells metastasis." (PMID 35938001, 2022). "Normal liver, thyroid gland, stomach, and colon were negative for RRM2 immunohistochemical staining, whereas tumor tissues were moderately stained." (PMID 36518297, 2022). "In addition, our results provide a new perspective that FRGs, including RRM2, influence anti-PDL1 immunotherapeutic responses by regulating immune checkpoint gene expression and infiltration of immune cells in the tumor microenvironment." (PMID 36153508, 2022).
tumor (continued). "Logistic regression analysis deciphered that RRM2 expression was correlated with tumor grade (p = 0.003) while it was not correlated with tumor stage (p = 0.207) in BLCA." (PMID 35740608, 2022). "The relative mRNA levels of RRM2 in tumor samples were much higher than those in normal samples, and also much higher in tumor tissues than those in corresponding adjacent nontumorous tissues." (PMID 33858512, 2021). "Additionally, the TOP2A, RRM2, NEK2, CDK1, and CCNB1 proteins were overexpressed in tumor liver tissues as compared to normal liver tissues according to the Human Protein Atlas database and previous studies." (PMID 34681056, 2021). "RRM2 and VEGF are both well-known targets for anti-tumor therapy." (PMID 34683911, 2021). "High RRM2 expression is closely related to tumor size and TNM stage, but not to the patient’s age and gender." (PMID 34895038, 2021). "Moreover, successful delivery of therapeutic siRNAs against RRM2 (siRRM2) and VEGF (siVEGF) led to downregulation of both genes, accompanied by the phenotypic changes of tumor and endometriotic cells." (PMID 34683911, 2021). "At present, only RRM2, CDK1 and CCNA2 were identified as tumor therapeutic targets." (PMID 33083112, 2020). "RRM2 showed no expression in both normal and tumor tissues, while CDC45, and CDC6 were mainly expressed in tumor cells and immune cells." (PMID 32969465, 2020). "We examined the expression of RRM2 by qRT-PCR in 40 tumor tissue samples and corresponding non-cancerous tissue samples from LUAD patients." (PMID 33411689, 2020). "In addition, we found that LUSC had higher RRM1 and RRM2 expression than LUAD, while RRM2B expressed lower in tumor tissues of LUSC than in those of LUAD." (PMID 31637211, 2019). "MP-HX downregulated the expression of genes that could promote anti-apoptotic effect, cell cycle progression, tumor development and progression, which include BIRC5, CCNA2, CCNB1, CCNB2, CCNE2, CDK1/2/6, GINS2, HELLS, MCM2/10 PLK1, RRM2 and SKP2." (PMID 30042885, 2018). "Quantification of RRM2 and p-ERK staining in tumor tissues was conducted." (PMID 28797284, 2017). "Adapting the tumour cell growth environment from an anchorage-dependent to -independent one resulted in decreased Chk1 protein expression as well as decreased Cdc6, CDT1 and RRM2 protein expression." (PMID 27775084, 2016). "Furthermore, RRM2 was more accurate than ki-67, HER2, lymph node involvement, tumor grade and uPA for classifying a subgroup of ER-negative breast cancer patients that were at higher risk." (PMID 25213022, 2014). "Tumour RRM1 and RRM2 mRNA expression levels ranged from 0.1 to 8.9 (median 1.04; mean 1.8±s.d." (PMID 18414411, 2008). "Further Western blot analysis showed that RRM2 regulated the expression levels of MMP2, MMP9 and EMT-related proteins (N-Cadherin, Vimentin, Snail), suggesting that RRM2 may promote tumor cell invasion and metastasis by promoting matrix degradation and inducing epithelial mesenchymal transition." (PMID 41333212, 2025). "c-MYC was elevated suggesting that RRM2-OE-TPC-1 cells may achieve the synergistic activation of multiple proliferative signaling pathways with the help of this transcription factor, accelerating tumor progression." (PMID 41333212, 2025). "Notably, miRNAs such as let-7f-5p, let-7b-3p, and let-7b-5p exhibited significant negative correlations with RRM2, implying their roles as tumor suppressors by down-regulating RRM2." (PMID 41357570, 2025). "Furthermore, targeting RRM2 could complement antiviral therapies in HBV/HCV-related HCC by concurrently suppressing viral replication and tumor progression." (PMID 40493217, 2025). "However, we did not observe significant correlations between RRM2 expression and patient gender, age, histopathological features, or tumor size." (PMID 40625451, 2024). "RRM2 was also revealed to function with its non-enzymatic roles in tumor progression." (PMID 39243109, 2024).
tumor (continued). "Meanwhile, RRM2 knockdown significantly reduced F-actin formation, whereas forced RRM2 expression promoted F-actin overgrowth in SMMC7721 and Huh7 cells, indicating that RRM2 plays an important role in cytoskeletal reorganization and facilitates tumor cell migration." (PMID 39766842, 2024). "In addition, our results revealed that RRM2 also presented an extensive cell membrane localization in the majority of iCCA tumor tissues, which has not been reported before." (PMID 39243109, 2024). "Significantly, RRM2 IHC staining was generally strong in most iCCA tumor tissues, but it was weak in hepatocytes and no staining in bile duct cells or other cells in the tumor microenvironment." (PMID 39243109, 2024). "Our analysis showed that RRM2 was not only significantly upregulated in NSCLC patients compared with healthy controls, but also that the serum RRM2 levels in NSCLC patients were associated with distant metastasis and histological type, but not with tumor size or lymph node metastasis." (PMID 37699023, 2023). "Furthermore, tumor biopsy from patients with metastatic melanoma showed that nanoparticles were localized in the tumor cells, but not in the surrounding normal epidermis and that RRM2 mRNA and protein levels were reduced." (PMID 34863235, 2021). "We next assessed whether the phenotype of the gemR models acquired in vivo differed from drug-sensitive counterparts with respect to expression of proteins involved in gemcitabine transport into tumor cells (hCNT1 and hENT1) or in gemcitabine metabolism (RRM1, RRM2, CDA, dCK)." (PMID 33073205, 2020). "However, expression of the acetyl-mimetic K95Q or QQQQ mutant RRM2 failed to rescue tumor growth compared with WT (panels 6 and 8 vs. panel 3), indicating that RRM2 acetylation at K95 suppresses tumor growth in vivo." (PMID 31324785, 2019). "Furthermore, ribonucleotide reductase (RR) is composed of dimerized large (RRM1) and small (RRM2) subunits and regulates intracellular pools of deoxy-CTP (dCTP), the expression of which leads to tumor cell resistance to nucleoside analogs, such as Ara-C treatment." (PMID 29141648, 2017). "The efficiency of RRM2 in predicting the outcome for patients with ER-negative breast cancer was compared with other prognostic markers for this subtype including ki-67, HER2, tumor invasiveness, lymph node involvement, distant organ metastasis, Elson histological stage and uPA." (PMID 25213022, 2014). "Importantly, for the first time, we revealed the correlations among RRM1, RRM2, and RRM2B expression during cancer development as well as their individual roles and collaborative relationships during cancer progression together with their prognosis with clinical tumor sample validation." (PMID 31637211, 2019). "However, the implication of the RRM2 in tumor angiogenesis is not closely studied." (PMID 19250552, 2009).